CD4 (CD4 molecule)
Diseases named in the same sentence as CD4 in open-access papers (continued):
Sharing a sentence is not in itself a finding about the gene and the disease.
pulmonary TB (214 papers, 2007 to 2026). "First, studies have confirmed a link between CD4 + TEM cell markers (GBP2 and LAG3) and the risk of pulmonary TB and COVID-19 infection, as the lungs are the primary sites affected by TB, and CD4 + T cells are closely related to TB." (PMID 40295296, 2025). "In this prospective study of 100 HIV-positive patients with TB, pulmonary TB predominated in those withCD4 counts >200, while extra pulmonary and disseminated TB were strongly associated with CD4 counts <200." (PMID 40978657, 2025). "Some studies have demonstrated that among HIV-infected patients with TB, having extrapulmonary TB—compared to pulmonary TB—was associated with lower CD4 T-lymphocyte counts." (PMID 38392836, 2024). "Comparatively, other authors found that PLWHA with a CD4 T-cell count of 200 cells/mm3 were at higher risk of developing advanced forms of OIs such as pulmonary TB." (PMID 38257785, 2024). "Most patients (94%) with a CD4 T-lymphocyte count <350 cells/mm3 were associated with extrapulmonary TB (p <0.0001), whilst most patients (78%) with a CD4 T-lymphocyte count >350 cells/mm3 were associated with pulmonary TB (p = 0.0011)." (PMID 38392836, 2024). "This reflects the fact that patients with low CD4 counts are more susceptible to pulmonary tuberculosis." (PMID 37667708, 2023). "The human immune deficiency virus (HIV) is the strongest risk factor for endogenous reactivation of pulmonary tuberculosis (PTB) through target reduction of CD4, T-lymphocytes, and cellular immune function." (PMID 35132323, 2022). "Our data demonstrate that the elevated proportion of peripheral blood CD4+CD25+CD127low Tregs is associated with the suppression of immune function among patients with active pulmonary TB." (PMID 36035072, 2022). "In this study, we dissected and quantified several different manifestations of pulmonary TB and analyzed how these manifestations are associated with quantitative parameters of Mtb-specific CD4+ cells and general leukocyte populations." (PMID 28871253, 2017). "Among twenty cases of histology-confirmed HIV-associated hepatic TB, median CD4 count was 47 cells/μl (inter-quartile range 27–107 cells/μl) and 75% (15/20) of patients had pre-existing pulmonary TB." (PMID 28148232, 2017). "Alcohol consumption contributes to development of pulmonary TB, favoring increased bacterial burden in lungs, besides causing a decrease in the number of CD4+ T cells and, consequently, lower release of IFN-y." (PMID 26901036, 2016). "While CD4 cell count was associated with both pulmonary TB and sputum mycobacterial burden in the univariable analyses, these associations did not persist in multivariable analyses." (PMID 23874476, 2013). "Low baseline CD4+ T-cell count (odds ratio [OR], 3.16, 95% confidence interval [CI], 2.19-4.58) and baseline extra pulmonary tuberculosis (OR, 7.7, 95% CI, 3.36-17.65) were associated with development of IRD." (PMID 21176160, 2010). "It has also been shown that alcohol use exacerbates murine pulmonary TB, which is associated with alterations in the region-specific CD4+- and CD8+-lymphocyte responses and defective lung granuloma formation." (PMID 19961618, 2009). "Regarding the CD4 T-lymphocyte count, most patients (94%) with <350 cells/mm3 were associated with extrapulmonary TB (p < 0.0001), whilst most patients (78%) with >350 cells/mm3 were associated with pulmonary TB (p = 0.0011)." (PMID 38392836, 2024). "The human immune deficiency virus (HIV) is the strongest risk factor for endogenous reactivation of pulmonary tuberculosis (PTB) through target reduction of CD4 and T-lymphocytes, with rapid bacilli reactivation after children are already exposed to infections." (PMID 35132323, 2022). "Similar to the effect on CD4+ T cells, helminth infections appear to exhibit a profound inhibitory effect on the expression of Th1 and Th17 associated cytokines in the context of pulmonary TB." (PMID 25211342, 2014).
pulmonary TB (continued). "Amongst 4,039 patients starting cART at a median CD4 count of 133 cells/mm3, there were 324 (8%) confirmed deaths, with an event rate of 28.83 (95% CI 25.78–32.15) deaths per 1000-person follow-up years; the commonest established causes were pulmonary TB and gastroenteritis." (PMID 25340766, 2014). "The expression of PD-L1 on CD14+ monocytes and PD-1 on CD4+ T cells are significantly higher in human pulmonary TB cases and positively correlated with higher bacterial burden and worse treatment outcomes." (PMID 40137709, 2025). "The median CD4 cell count was significantly lower in case of extra-pulmonary TB (67 [24–84 cells/mm3]) than in pulmonary forms (89 [56–138 cells/mm3]) (p = 0.01)." (PMID 40357181, 2025). "Several markers of advanced HIV disease strongly predicted increased mortality risk, including poor functional status, extra-pulmonary TB, late WHO stage, and severe immunosuppression defined by low CD4 counts." (PMID 39095740, 2024). "Ninety-four percent of patients with extrapulmonary TB had a CD4 T lymphocyte count <350 cells/mm3, while seventy-eight percent of patients with pulmonary TB had a CD4 T lymphocyte count <350 cells/mm3." (PMID 38787280, 2024). "Baseline characteristics were median age 35 years (interquartile range [IQR], 29-43), 40% female, 69% pulmonary TB only, median CD4, 102 (IQR, 38-239) cells/mm3, and median HIV RNA, 5.5 (IQR, 5.0-5.8) log copies/mL." (PMID 38486816, 2024). "Most HIV-infected patients (73%) had extrapulmonary TB and most (94%) patients with extrapulmonary TB had a CD4 T-lymphocyte count < 350 cells/mm3; in contrast, most (78%) of the patients with pulmonary TB had a CD4 T-lymphocyte count > 350 cells/mm3." (PMID 38392836, 2024). "People living with HIV with a history of active pulmonary TB have more HIV pro-virus in their circulating CD4+ T cells, even years after TB cure." (PMID 39345793, 2024). "While the role of IL-20 cytokines in TB is poorly investigated, one report demonstrated that IL-19 and IL-24 are elevated in pulmonary TB patients and in vitro neutralization of these cytokines resulted in an enhanced CD4+ Th1/Th17 responses." (PMID 38162636, 2023). "It has been shown that the recruitment of CD4+ cells in the lungs is essential for the development of a protective granulomatous response to pulmonary TB." (PMID 36676177, 2023). "Socio-demographic factors (age, sex), history of pulmonary tuberculosis, smoking, substance use, time of HAART initiation, CD4 count, viral load, and HAART have been crudely associated with pulmonary disease development and progression in PLHIV." (PMID 37901155, 2023). "In the current study, we examined the correlation between the proportion of CD4+CD25+CD127low Tregs and the clinical characteristics of active pulmonary TB patients, so as to investigate the significance of CD4+CD25+CD127low Tregs in the development of TB." (PMID 36035072, 2022). "Further differential diagnostic process revealed pulmonary TB in the course of advanced HIV-1 disease, with a CD4+ T-lymphocyte count of 107 cells/mm3." (PMID 36010236, 2022). "About 30.0% (15/50) of smokers, 32.86% (23/70) cases with previous pulmonary tuberculosis, and 52.38% (11/21) with CD4 count < 200 cells/μl had bacterial LRTIs." (PMID 35672713, 2022). "The negative costimulatory signal PD-1/PD-L1 expression is downregulated among active pulmonary TB patients, which is involved in the proliferation of CD4+CD25+CD127low Tregs." (PMID 36035072, 2022). "A total of 263 PLHA with LRTIs were enrolled in this study, out of which, 50 were smokers, 70 had previous pulmonary tuberculosis, and 21 had CD4 count < 200 cells/μl." (PMID 35672713, 2022). "We examined the proportions of peripheral blood CD4+CD25+CD127low Tregs among active pulmonary TB patients with different clinical characteristics." (PMID 36035072, 2022).
pulmonary TB (continued). "Our present study addresses the dynamics of the expression of activation and maturation markers on MTB-specific CD4+ T-cells in well characterized pulmonary TB patients upon TB treatment initiation in a high TB and HIV endemic setting." (PMID 36145465, 2022). "The earlier study also found a link between pulmonary tuberculosis and the number of CD4+ cells in HIV patients and the amount of virus in their blood." (PMID 35913968, 2022). "Systematic and meta-analysis suggested there was a decreased CD4/CD8 ratio in the peripheral blood of pulmonary tuberculosis patients." (PMID 35681174, 2022). "Flow cytometry detected a higher proportion of peripheral blood CD4+CD25+CD127low Tregs among active pulmonary TB patients with a positive anti-M." (PMID 36035072, 2022). "In summary, the results of the present study demonstrate a higher proportion of CD4+CD25+CD127low Tregs in patients with active pulmonary TB than in healthy controls." (PMID 36035072, 2022). "HIV-positive individuals with normal CD4+ T cell counts manifest traditional symptoms of pulmonary TB, such as pleural effusions and lymph node lesion, while few symptoms restricted to the pulmonary apices also occur." (PMID 35130846, 2022). "Levels of CD4+ T cells have been correlated with the pattern of manifestation of pulmonary TB, finding that those with CD4+ count <200 were more likely to produce atypical patterns." (PMID 34336428, 2021). "In mouse models and in humans with active pulmonary tuberculosis, both IL-17- and IL-22-producing CD4+ T cells as well as IL-17+γδ T cells were shown to contribute to the antimycobacterial immune response." (PMID 34054347, 2021). "The authors indicated that IL-17 levels produced by CD4+ in response to M.tb antigens stimulation were lower in pulmonary TB cases compared to healthy controls and healthy tuberculin reactors." (PMID 33923293, 2021). "A high frequency of CD4+CD25highFoxP3+ cells was observed in patients with active pulmonary tuberculosis when compared to healthy control and LTBI subjects, and when LTBI patients were compared to healthy controls (p<0.05)." (PMID 34324509, 2021). "In mouse models and in humans with active pulmonary tuberculosis, both IL-17- and IL-22-producing CD4+ T cells and IL-17+γδ T cells were shown to contribute to the antimycobacterial immune response." (PMID 34054347, 2021). "The aim of this study was to explore the role of β-catenin in CD4+ T cells and its expression characteristics in patients with pulmonary tuberculosis (PTB)." (PMID 33628846, 2021). "On the other hand, Th17/FoxP3 ratio positively correlated with greater values of total and nadir CD4 + T cell counts and with pulmonary TB." (PMID 31906962, 2020). "In HIV-positive patients, high levels of D-dimer, a low number of CD4-positive T cells, high dose of HIV virus, low body mass index, and sputum smear-positive pulmonary TB have been known as risk factors of IRIS." (PMID 31905985, 2019). "In a study in Kenya, LAM alone diagnosed 58% of ambulatory patients with CD4 < 200 cells/μl and microbiologically confirmed pulmonary TB." (PMID 31039161, 2019). "Pulmonary TB (PTB) is more frequently seen than extrapulmonary TB (EPTB) in patients with relatively intact immune function (CD4+ count > 200/mm3)." (PMID 30915136, 2018). "Our results did not underline clear preference for the use of LF-LAM to diagnose pulmonary TB in HIV+ patients with CD4 cells count <200/mm3, from a strictly economic point of view." (PMID 30024890, 2018). "In a similar study in North India, it was also reported that pulmonary TB and pyogenic pneumonia were present in over a wide range of CD4 count, but their incidence increased as the CD4 count declined." (PMID 29941015, 2018). "Several studies have demonstrated the presence of functional Mtb-specific CD4+ T cell responses in treatment-naïve pulmonary TB patients by assessing the production of IL-2, TNF-α, and IFN-γ in PBMCs stimulated with Mtb antigens." (PMID 29983703, 2018).
pulmonary TB (continued). "CD4+FOXP3+ T regulatory cells (Tregs) have been reported to be increased in patients with pulmonary tuberculosis." (PMID 29489879, 2018). "Pulmonary TB was observed in a 5 year old congenital HIV infected patient during ART with CD4% above 25%." (PMID 28443591, 2017). "Similar to pulmonary TB, ocular TB occurred over a wide range of CD4 count, although it was more common in patients with CD4 count below 300 cells/mm3." (PMID 27051539, 2016). "Levels of mir-32 were lower in PP vs NN groups in the present study while previous studies on bovine and human pulmonary tuberculosis reported the overexpression of mir-32 in infected alveolar macrophages and CD4+ T cells." (PMID 27760169, 2016). "Among 675 HIV-infected adults with median CD4 of 213/mm3 (interquartile range 85-360/mm3), 123 (18%) had culture-confirmed pulmonary TB." (PMID 27842535, 2016). "Recently, decreased frequencies of CD4+CXCR5+ T helper cells were reported in the blood of active pulmonary TB patients when compared with the blood of latent TB patients." (PMID 26785168, 2016). "The risk factors most consistently implicated in the development of TB-IRIS are a low pre-ART CD4 count, short duration between starting TB treatment and ART, and extra-pulmonary TB." (PMID 27677424, 2016). "Another study confirmed an increase in CD4+ Treg frequencies in patients previously treated for extra-pulmonary TB compared to pulmonary TB, but reported an analogous increase in CD4+ activation markers." (PMID 26029205, 2015). "During TB therapy, circulating CD4+ Treg frequencies declined as mentioned; however, this was only noted following chemotherapy for pulmonary TB." (PMID 26029205, 2015). "He had commenced treatment in November 2009 with WHO clinical stage 3 (concurrent pulmonary TB) and baseline CD4+ cell count of 172 cells/μL." (PMID 24606875, 2014). "It is intriguing that COPD subjects had increased percentages of a different subset of lung CD4+ cells, CD62L−, CD27+ cells, which in a murine model of pulmonary tuberculosis have been linked to defective IFN-γ production." (PMID 24805101, 2014). "Thirty-one (26.3%) patients had associated pulmonary tuberculosis and 25 (21.2%) patients were HIV positive with a median CD4+ count of 225 cells /μl." (PMID 23497503, 2013). "This study has revealed that various radiographic manifestations of HIV coinfected with pulmonary TB are related to the level of immunosuppression (CD4 count)." (PMID 23431432, 2013). "To study this question, we enrolled 50 HIV-negative subjects with AFB smear-positive pulmonary TB and measured the Mtb specific CD4+ and CD8+ T cell responses at three time points during antituberculosis treatment." (PMID 24324704, 2013). "This study was undertaken to determine the effect of low CD4+ lymphocyte count on the radiographic patterns of HIV patients with pulmonary TB among Nigerians." (PMID 23431432, 2013). "Of 71 HIV infected patients, 28.2 percent were diagnosed with pulmonary tuberculosis, had the mean age of 31 ± 4.3 which range 18 to 43 years and their mean CD4 count was 143.95 cells per ml which range 26 to 506 cells per ml." (PMID 23487151, 2013). "Patients with baseline CD4 cell counts below 500 cells/mm3 were significantly more likely to have smear positive pulmonary TB (adjusted OR 1.6, IQR 1.2-2-3)." (PMID 24358268, 2013). "Disseminated pulmonary TB, lower BMI, WHO clinical stage 4 and lower CD4 count were found to be associated with increased risk of developing anti-TB drugs induced hepatotoxicity on bivariate analyses." (PMID 23696901, 2013). "Among patient baseline characteristics, female sex, lower BMI, smear-positive pulmonary TB, lower CD4 count and higher HIV-1 RNA viral load were independently associated with the occurrence of TB-IRIS." (PMID 24367678, 2013). "We found that pulmonary TB patients had significantly elevated CD244/2B4 expression on M. tuberculosis antigen-specific CD4+ T cells compared with latent infection individuals." (PMID 23638187, 2013).
pulmonary TB (continued). "In pulmonary tuberculosis patients, CD4+CD25+Foxp3+Treg and TGF- β1 increase, demonstrating that the immune status in these patients is low, and that the pathogen, M. tuberculosis, cannot be effectively eradicated." (PMID 23755239, 2013). "Highly differentiated CD27low Mtb-specific (CD27lowIFN-γ+) CD4 T cells accumulate in the lungs and circulate in the blood of patients with active pulmonary TB." (PMID 22937086, 2012). "We screened all patients irrespective of the presence or absence of symptoms and reported a high prevalence of sputum culture-positive pulmonary tuberculosis in patients with CD4 counts less than 200 cells per μL." (PMID 22015305, 2012). "Assessment of the TNF-α/IL-2 ratio derived of CD4+ T cells revealed increased TNF-α in patients suffering from extra-pulmonary TB, suggesting a more pro-inflammatory cytokine profile if compared to pulmonary TB." (PMID 22523581, 2012). "It has been shown that the leading part in immune suppression at infiltrative, dissemination, and fibrosis-cavity pulmonary tuberculosis is played by natural regulatory CD4+CD25+Foxp3+-T lymphocytes." (PMID 22666578, 2012). "Twenty-seven (41.5%) children had advanced (stage 3) or severe (stage 4) clinical disease, 18 of whom were also severely immunosuppressed (baseline CD4% <15%) and 9 of whom had pulmonary tuberculosis." (PMID 22770231, 2012). "Increases in the CD4+/CD8+ ratio of T lymphocytes in BALF from active pulmonary TB patients, as compared to controls, have previously been reported." (PMID 22889060, 2012). "It has been demonstrated that in patients with fibrocavernous and infiltrative form of the disease and drug-resistant pulmonary tuberculosis the number of CD4+CD25−Foxp3+-regulatory T cells was increasing." (PMID 22666578, 2012). "Differences between extra-pulmonary and pulmonary TB were minor when assessing one cytokine expressing CD4+ T cells and – unexpectedly - restricted to differences among CD8+ T cells." (PMID 22523581, 2012). "A recent prospective study evaluating the prevalence of active TB in HIV infected patients with a CD4 cell count of > 200 cells/μl reported that 29% of those with culture- confirmed pulmonary TB had normal radiography and clinical examination." (PMID 22277087, 2012). "In humans, patients with active pulmonary TB have higher frequency of CD27lowMtb-specific CD4 T cells than latently- infected individuals." (PMID 22937086, 2012). "At baseline, men tended to be older, had lower CD4 baseline values, more advanced disease, had pulmonary tuberculosis and had received less treatment follow up (all at p < 0.001)." (PMID 22050673, 2011). "In contrast, Brenda et.al have reported a progressive increase in the frequency of extra pulmonary TB as CD4 cell count decreases suggesting that CD4 cells play a major role in limiting the severity of TB." (PMID 21814542, 2011). "As per 2006 guidelines, all HIV-infected persons with extra pulmonary (EPTB) or disseminated TB and HIV-infected pulmonary tuberculosis (PTB) patients with a CD4-lymphocyte count ≤350/mm3 are considered eligible for ART." (PMID 21931674, 2011). "In summary, in this descriptive flow cytometry study, we have observed severe phenotypic abnormalities of T cells in patients with active pulmonary tuberculosis including severe depletion of CD4 and CD8 T-cell counts." (PMID 22567259, 2010). "The median CD4+ T-lymphocyte count was 49 cells/μl and 126 (53%) patients were diagnosed with active pulmonary tuberculosis." (PMID 20302657, 2010). "No single factor, including respiratory symptoms, physical findings, CD4+ T-cell count, or chest radiographic abnormalities, substantially increased or decreased the likelihood of pulmonary tuberculosis." (PMID 20361038, 2010). "This is consistent with the report describing distinct IL-22 and IL-17 producing Th17 cells among CD4 T cells in active pulmonary TB patients." (PMID 20195465, 2010).